CR1 (complement C3b/C4b receptor 1 (Knops blood group))
Diseases named in the same sentence as CR1 in open-access papers (continued):
Sharing a sentence is not in itself a finding about the gene and the disease.
delirium (1 paper, 2026). A disorder characterized by confusion; inattentiveness; disorientation; illusions; hallucinations; agitation; and in some instances autonomic nervous system overactivity. "In our study, CR1 plasma protein levels had a nominally significant association with incident delirium (P = 0.013)." (PMID 41286463, 2026). "Nonetheless, our findings suggest newly identified genes (for example MS4A4A, CR1 and TOMM40) that may be of relevance to future delirium research and therapeutic targets investigations." (PMID 41286463, 2026).
depression (1 paper, 2017). "While some previous studies have found associations between the single, large-effect AD risk genes APOE and CR1, and depression, other studies failed to report this;30, 31 these small-sample, primarily candidate gene studies do not provide convincing evidence." (PMID 28418403, 2017).
E. coli infection (1 paper, 2023). "The phagocytosis-promoting receptors were upregulated after E. coli infection, including complement receptor (CR1, CR3, and iC3b), integrins (αMβ2, αVβ3, and αVβ5), toll-like receptor (TLR2, TLR4, and TLR6), might accelerate the phagosome maturation." (PMID 36411420, 2023).
glioblastoma (1 paper, 2024). The most malignant astrocytic tumor (WHO grade IV). "A similar anatomical phenomenology has been reported in glioblastoma tumors co-localizing CR1 (Millipore rabbit polyclonal anti-CR1 antibody) with CD31 (endothelial cell marker) via confocal microscopy, without mentioning issues of CR1 vs. CR3 expression." (PMID 39518018, 2024).
glioma (1 paper, 2018). A benign or malignant brain and spinal cord tumor that arises from glial cells (astrocytes, oligodendrocytes, ependymal cells). "CR-1 and Nodal are capable of enhancing the progression and invasion of glioma cells by activating Smad signaling pathway." (PMID 30373174, 2018).
glomerulonephritis (1 paper, 2009). A renal disorder characterized by damage in the glomeruli. "We compared the expression of three podocyte markers, i.e.: synaptopodin (SYN), CR1 and neprilysin (NEP) in 107 patients with different forms of glomerulonephritis (GN) and 5 normal kidneys (NK)." (PMID 23675111, 2009).
Granuloma (1 paper, 2016). A compact, organized collection of mature mononuclear phagocytes, which may be but is not necessarily accompanied by accessory features such as necrosis. "CR1 was found on the surface of 22–39% of the macrophages, both with and without acid-fast BCG-mycobacteria, and 9–13% of the dendritic cells in mouse granulomas." (PMID 27066505, 2016).
idiopathic pulmonary fibrosis (1 paper, 2020). Idiopathic pulmonary fibrosis (IPF) is a nonneoplastic pulmonary disease that is characterized by the formation of scar tissue within the lungs in the absence of any known cause. "A CR1 polymorphism was associated with development of idiopathic pulmonary fibrosis." (PMID 33362763, 2020).
injury (1 paper, 2020). Damage inflicted on the body as the direct or indirect result of an external force, with or without disruption of structural continuity. "CR1 and CD59 were significantly reduced in the first week after acute brain injury." (PMID 33362763, 2020).
Intellectual disability (1 paper, 2021). "In addition, overexpression of Ln-CR1 greatly increase expression of Ebf3, a gene reported to be associated with Intellectual Disability." (PMID 33760820, 2021).
late-onset Alzheimers disease (1 paper, 2011). This is the most common form of the disease, which happens to people age 65 and older. "Recent GWAS and subsequent confirmation studies reported several single-nucleotide polymorphisms (SNPs) at the CLU, CR1 and PICALM loci in association with late-onset Alzheimer's disease (AD)." (PMID 21912625, 2011).
latent infection (1 paper, 2015). "Interactions between EBVgp350/220 and complement receptor type 2 (CR2)/CD21 and/or (CR1)/CD35 on B-cells is required for cellular attachment and initiation of latent infection." (PMID 25885535, 2015).
leiomyosarcoma of the uterus (1 paper, 2021). "Ectopic expression of the CR-1 transgene in mammary glands induced mammary hyperplasia and adenocarcinoma in the WAP-CR-1 or MMTV-CR-1 transgenic mice and leiomyosarcoma of the uterus in the MMTV-CR-1 transgenic mice." (PMID 34517344, 2021).
lung diseases (1 paper, 2024). "A recent study demonstrated that nine genes (CD274, CEACAM1, CR1, FCGR1A/B, IFITM1, IRAK3, LILRA6, MAPK14, and PDCD1LG2) showed 100% sensitivity and specificity that distinguished patients with active TB from those with other lung diseases (OPD)." (PMID 38674369, 2024).
Malaria resistance (1 paper, 2024). "CR1 deficiency was also related to Malaria resistance, which can greatly reduce the resetting of the rosette." (PMID 38665582, 2024).
metastatic cancers (1 paper, 2024). A carcinoma which has spread from the original site of growth to another anatomic site. "Evaluating CR1 expression in M0 vs. M1 prostate CA, here again we saw an ability to discriminate non-metastatic from metastatic cancers base on CR1 IHC staining intensity, with “p” value = 0.0094." (PMID 39518018, 2024).
multiple myeloma (1 paper, 2018). "Interestingly, CR1 which is expressed by podocytes, emerges as a novel disease-relevant target in C3G and auto-antibodies targeting CR1 have been found in patients with multiple myeloma." (PMID 30333829, 2018).
neuroblastoma (1 paper, 2023). Neuroblastoma (NB) is the most common solid, extracranial childhood tumor. "CR1 mRNA was detected at the expected product size by qRT‐PCR in both HMC3 and IMhu microglial lines and the monocyte cell line, THP1; the neuroblastoma line, SH‐SY5Y, gave no product." (PMID 36825534, 2023).
Obesity (1 paper, 2022). Accumulation of substantial excess body fat. "Thus, the result of this study shows that by blocking the CR1 we can get the beneficial effect of the constituents (punarnavine, boeravinone B, and eupalitin) as a potent anti-obesity agent." (PMID 35567159, 2022).
otitis media (1 paper, 2019). Inflammation of the anatomical structures of the middle ear, which is most often caused by an infectious process. "Two differentially expressed genes CR1 and SAA1 overlap in middle ear, sinus, and lower airway samples and are potentially novel genes for otitis media susceptibility." (PMID 32010199, 2019).
pancreatic ductal adenocarcinoma (1 paper, 2021). An infiltrating adenocarcinoma that arises from the epithelial cells of the pancreas. "A recent study by Chan and colleagues found that CR-1-31-B treatment reduced the viability of pancreatic ductal adenocarcinoma (PDAC) organoids and suppressed tumor growth in a rodent PDAC model." (PMID 33540613, 2021).
Plasmodium falciparum malaria (1 paper, 2005). Malaria resulting from infection by Plasmodium falciparum. "It has been hypothesized that the African alleles Sl2 and McCb of the Swain-Langley (Sl) and McCoy (McC) blood group antigens of the complement receptor 1 (CR1) may confer a survival advantage in the setting of Plasmodium falciparum malaria, but this has not been demonstrated." (PMID 16277654, 2005).
pneumococcal pneumonia (1 paper, 2006). A febrile disease caused by STREPTOCOCCUS PNEUMONIAE. "The mean expression of complement receptor 1 (CR1) on neutrophils was significantly higher in the patients with pneumococcal pneumonia than in those with influenza A pneumonia." (PMID 16433910, 2006). "The main finding of the present study was that the expression of CR1 on neutrophils was significantly higher in the patients with pneumococcal pneumonia than in those with influenza A pneumonia." (PMID 16433910, 2006). "The mean expression of CR1 on neutrophils was significantly higher in the patients with pneumococcal pneumonia than in those with influenza A pneumonia." (PMID 16433910, 2006).
preeclampsia (1 paper, 2025). Preeclampsia is a hypertensive disorder of pregnancy that is characterized by new-onset hypertension with proteinuria presenting after 20 weeks of gestation, and depending on mild or severe forms may initially present with severe headache, visual disturbances, and hyperreflexia. "Around the same time, Burwick and Feinberg were the first to show that C5 blockade with eculizumab could also be used effectively to treat preeclampsia and HELLP syndrome, consistent with the protective effects seen with soluble CR1 and C5a antagonism in animal models." (PMID 40777009, 2025).
primary Sjögren’s syndrome (1 paper, 2025). "In our study, we performed the first explicit analysis of the CR1 expression in conjunctiva with Sjögren’s syndrome, revealing that CR1 expression was significantly higher compared to normal controls." (PMID 40149556, 2025). "In a study on CR1 levels in patients with primary Sjögren’s syndrome, CR1 levels varied within a wide range (20–124%), with a notable prevalence of lower CR1 levels among affected individuals." (PMID 40149556, 2025).
Rickettsia infection (1 paper, 2018). "Since infection in CR1/2−/− mice did not demonstrate increased morbidity or rickettsial load, we conclude that CR1/2−/− mice do not have a deficient immune response to Rickettsia infection." (PMID 29581196, 2018).
sinusitis (1 paper, 2019). An acute or chronic inflammatory process affecting the mucous membranes of any sinus cavity. "In CRS, CR1 was reported to have denser localization in the mucosa of CRS patients than in normal mucosa, and higher levels of CR1 were found in granulocytes from the circulation and sinus pus in patients with purulent sinusitis." (PMID 32010199, 2019).
synucleinopathies (1 paper, 2024). "Beyond known PD genes GBA1 and LRRK2, rare variants AD genes (CD33, CR1 and PSEN2) and Aβ toxicity modifiers involved in RhoA/actin cytoskeleton regulation (ARGHEF1, ARHGEF28, MICAL3, PASK, PKN2, PSEN2) were shared risk factors across synucleinopathies." (PMID 38496508, 2024).
T-cell leukemia (1 paper, 2017). A malignant disease of the T-lymphocytes in the bone marrow, thymus, and/or blood. "Evidence for a CR2 and CR1 function in T cells was their 3- to 10-fold enhancement of C3-dependent HIV infection in the HPB-ALL T cell leukemia cell line." (PMID 28814669, 2017).
teratoma (1 paper, 2024). A non-seminomatous germ cell tumor characterized by the presence of various tissues which correspond to the different germinal layers (endoderm, mesoderm, and ectoderm). "However, relative to HM-KO teratomas, HM-KO comp, NK, and CR1 comp teratomas each persisted for longer and grew larger." (PMID 38215755, 2024).
thymoma (1 paper, 2024). A neoplasm arising from the epithelial cells of the thymus. "CD55 and CR1 were considerably downregulated in thymoma patients." (PMID 39434140, 2024).
uveitis (1 paper, 2025). An inflammatory process affecting a part of or the entire uvea. "Notably, GNLY and CR1 displayed inverse regulation patterns, being upregulated in the uveitis-only group but downregulated in the systemic disease-associated uveitis group." (PMID 40270958, 2025). "Importantly, only three IRGs (CR1, CST7, and GNLY, all regulated by IFN types I and II) were differentially expressed in both uveitis groups, differing on regulation among groups." (PMID 40270958, 2025).
tumor (81 papers, 1990 to 2026). "Many studies have shown that CR‐1 is associated with the metastasis of many human tumours carcinomas." (PMID 37528674, 2023). "In the study population, 54 (36.49%) patients developed distant metastasis at different time intervals after surgery, which was associated with the level of CR‐1 expression in tumour." (PMID 32697011, 2020). "In our IHC analysis, high CR-1 expression is associated significantly with aggressive tumor phenotype, which suggest that CR-1 expression may be vital for the acquisition of malignant potential in ccRCCs." (PMID 31455359, 2019). "CRIPTO (or CR-1 or TDGF1) is a protein that plays an active role in tumor initiation and progression." (PMID 39592836, 2025). "Phagocytes infected with Fn, after forming a special CX3 CR1 + PD-L1 + subpopulation, are continuously recruited to the tumor site." (PMID 40381082, 2025). "In summary, lysozyme inhibition is the initial step in this process, while CX3 CR1 and PD-L1 mediate the key steps in the transformation of phagocytes to a pro-tumor phenotype." (PMID 40381082, 2025). "Our collective IHC data suggest that CR3 is more highly expressed in clinical specimens than CR1 and its staining is always more intense in human tumor tissue." (PMID 39518018, 2024). "These reagents were then used for the IHC staining of pathological microarray cancer tissue, WB analysis of tumor cell lines, capture/quantitative ELISA analysis, and CR1/CR3 interactive binding protein studies." (PMID 39518018, 2024). "CR1 is known to mediate tumor cell growth through a series of signal transduction pathways, including a Nodal-dependent Smad2/3 mechanism or Nodal-independent events encompassing Src, ras/raf/MAPK, and PI3K/Akt." (PMID 39518018, 2024). "In our WB analysis of human tumor cell lines, a 50 kDa MW band for CR1 was consistently identified in all tested cells except for hmVEC extracts." (PMID 39518018, 2024). "As CR1 levels go up in inflammation or carcinogenesis, binding protein become saturated, and free CR1 molecules become available for older antibody interaction (i.e., IHC staining of tumor tissue)." (PMID 39518018, 2024). "CR‐1 promotes proliferation, survival, migration, and invasion of tumor cells and tumor angiogenesis." (PMID 35949510, 2022). "An inhibitor of eukaryotic translation initiation factor 4A, CR-1–31B, has a synergistic effect on inhibiting the growth of tumor cells and inducing apoptosis in drug combination therapy." (PMID 35252179, 2022). "Cripto‐1 (CR‐1) facilitates vascular endothelial growth factor (VEGF) expression, and these markers are associated with various tumor cell proliferation, angiogenesis, and metastasis." (PMID 35949510, 2022). "In recent years, CR‐1 has been shown an early tumor marker for diagnosis of breast and colon cancer." (PMID 35949510, 2022). "The significant increase of serum CR‐1 level in patients with distant metastasis theoretically indicates that angiogenesis is a necessary condition for tumor progression." (PMID 35949510, 2022). "The mice injected with CR-1 overexpressing BEL-7402 cells showed significantly larger tumor volumes, tumor sizes, and tumor weights compared to those injected with control vector-transduced BEL-7402 cells." (PMID 34517344, 2021). "By using in vivo tetracycline inducible silencing of CR-1 they also found that Cr-1 knockdown CSCs generates smaller tumor masses, with fewer CSCs and a dramatically reduced ability to generate metastasis compared to non-induced controls." (PMID 34360603, 2021). "Our results also demonstrated that the truncated 1.7-kb CR-1 transcript was predominantly expressed in the adjacent non-tumor liver and primary HCC tissues." (PMID 34517344, 2021). "On the contrary, the surface expression of CR-1 (as well as its secretion in the tumor microenvironment) tends to oscillate during spheroids culture." (PMID 34360603, 2021).
tumor (continued). "CR-1 over-expression significantly increased in vivo xenograft tumor growth of HCC cells in nude mice and in vitro HCC cell proliferation, migration, and invasion." (PMID 34517344, 2021). "RT-PCR analysis demonstrated that CR-1 transcripts were significantly up-regulated in HCC tissues compared to adjacent non-tumor liver tissues." (PMID 34517344, 2021). "Only the hypomethylated/upregulated gene ID1 and the hypermethylated/downregulated gene CR1 were both carcinogenic and tumor suppressor genes." (PMID 33833773, 2021). "The authors not only elegantly demonstrated that this regulation is coordinated in the entire tumor mass, but also that CR-1-silenced cells generate smaller colonies in soft-agar assays." (PMID 34360603, 2021). "CR1 promotes the tumor growth of colorectal CSC/progenitors in vivo and in vitro, by activating the Glypican/Src/AKT pathway and inducing CD44 expression." (PMID 32456226, 2020). "Increasing the Cripto-1 (CR-1)-expressing subpopulation by activin/nodal signaling enhances tumor-forming ability by promoting self-renewal potential." (PMID 32456226, 2020). "We found that the expression level of CR‐1 was correlated with tumour differentiation and tumour size significantly (P = .043 and .033)." (PMID 32697011, 2020). "The average content of CR‐1 expression was (1.39 ± 0.87) ng/mL of tumours for low and (2.82 ± 1.73) ng/mL for high, which were statistically significant different (P = .017)." (PMID 32697011, 2020). "There was correlation found between the CR‐1 and tumour size and tumour differentiation, thus supporting the contention that the prognostic significance of CR‐1 expression is consistent with that of these conventional prognostic indicators." (PMID 32697011, 2020). "As compared to the matched adjacent non-tumor tissues, a statistically significant elevation of CR-1 mRNA was detected in tumors (P < 0.001)." (PMID 31455359, 2019). "The results indicated that high CR-1 expression was 125/205 (60.9%) in ccRCC tissues compared with 39/205 (19.1%) in adjacent non-tumor tissues (P < 0.001)." (PMID 31455359, 2019). "We found CR-1 expression was elevated in ccRCC cell lines, tumor tissues, and serum samples from ccRCC patients." (PMID 31455359, 2019). "In both studies, tumor tissues and patient-matched blood samples have been analyzed, showing that high CR-1 levels in the plasma correspond to re-expression of CR-1 in tumor tissues." (PMID 31455359, 2019). "Compared to the adjacent non-tumor tissues, the IHC score of CR-1 was significantly higher in the ccRCC tissues (6.26 ± 3.25 vs 2.63 ± 2.67, P < 0.001)." (PMID 31455359, 2019). "The CR-1 expression was first measured in 38 matched pairs of adjacent non-tumor tissue samples and fresh ccRCC samples." (PMID 31455359, 2019). "Apart from the difference in tumor volume and weight, we also found the control group exhibited much stronger CR-1 and Ki-67 staining, as detected by IHC." (PMID 31455359, 2019). "In conclusion, we have for the first time provided evidence that ccRCC patients displayed upregulation of CR-1 in tumor tissues and increased serum CR-1 levels." (PMID 31455359, 2019). "First, IHC analysis of clinical samples indicated that there was a positive correlation between CR-1 expression and aggressive tumor phenotype and poor survival." (PMID 31455359, 2019). "High CR-1 expression was found in 125 of the 205 (60.9%) ccRCC specimens, compared with 39/205 (19.1%) in adjacent non-tumor tissues (P < 0.001)." (PMID 31455359, 2019). "CR-1 inhibition by different approaches always resulted in inhibition of cancer cell proliferation in vitro and of tumor growth in vivo." (PMID 31455359, 2019). "Accordingly, the present study aimed to evaluate the clinical significance of CR-1 in both serum and tumor tissues in ccRCC." (PMID 31455359, 2019). "Similar to the mRNA results, CR-1 protein was also significantly increased in tumor tissues than in adjacent non-tumor tissues (P < 0.001)." (PMID 31455359, 2019).